ARF4 (ARF GTPase 4)
Description:
GTP-binding protein that functions as an allosteric activator of the cholera toxin catalytic subunit, an ADP-ribosyltransferase. Involved in protein trafficking; may modulate vesicle budding and uncoating within the Golgi apparatus. Part of the ciliary targeting complex containing Rab11, ASAP1, Rabin8/RAB3IP, RAB11FIP3 and ARF4, which direct preciliary vesicle trafficking to mother centriole and ciliogenesis initiation.
Synonyms: ARF2
Tractability: Small molecule: a structure with a bound ligand is known. Antibody: its Gene Ontology location is reachable by antibodies, with medium confidence. PROTAC: ubiquitination databases record sites on it; its protein half-life has been measured.
Gene: Protein-coding gene on chromosome 3 (57,571,363 to 57,598,220, reverse strand). Ensembl gene ENSG00000168374.
Subcellular location: Golgi apparatus; Membrane
Pathways (Reactome):
Vesicle-mediated transport: COPI-dependent Golgi-to-ER retrograde traffic; COPI-mediated anterograde transport
Organelle biogenesis and maintenance: VxPx cargo-targeting to cilium
Gene Ontology:
Molecular function: epidermal growth factor receptor binding; GTP binding; NAD+-protein-arginine ADP-ribosyltransferase activity; phospholipase D activator activity; protein binding; GTPase activity; guanyl-nucleotide exchange factor activity
Biological process: cell migration; dendritic spine development; negative regulation of apoptotic process; positive regulation of transcription by RNA polymerase II; regulation of cilium assembly; regulation of reactive oxygen species metabolic process; retrograde vesicle-mediated transport, Golgi to endoplasmic reticulum; cilium assembly; endoplasmic reticulum to Golgi vesicle-mediated transport; intracellular protein transport; epidermal growth factor receptor signaling pathway; regulation of postsynapse organization; regulation of synapse organization; response to axon injury
Cellular component: cytosol; dendritic spine; extracellular exosome; Golgi apparatus; Golgi membrane; membrane; ruffle membrane; plasma membrane; cytoplasm; glutamatergic synapse
Genetic constraint (gnomAD): Loss-of-function variants: 2 observed, 15.07 expected, observed/expected ratio (o/e) 0.13, 90% interval 0.053 to 0.42. The upper end of that interval is the gene's LOEUF score, 0.42, which puts it in group 1 of 6, group 1 being the genes least tolerant of losing a copy. Missense variants: 90 observed, 187.4 expected, observed/expected ratio (o/e) 0.48, 90% interval 0.4 to 0.57. Synonymous variants: 52 observed, 67.1 expected, observed/expected ratio (o/e) 0.77, 90% interval 0.62 to 0.98.
Homologues: Orthologues: chimpanzee ARF4 (100% identical), macaque ARF4 (100% identical), dog ARF4 (95% identical), pig ARF4 (95% identical), tropical clawed frog arf4 (95% identical), mouse Arf4 (94% identical), rat Arf4 (94% identical). Paralogues in human: ARF5 (88% identical), ARF1 (80% identical), ARF3 (79% identical), ARF6 (64% identical), TRIM23 (57% identical), ARL1 (57% identical), ARL4C (47% identical), ARL2 (46% identical), ARL4A (46% identical), ARL5A (44% identical), ARL3 (44% identical), ARL5B (44% identical), and 18 more.